TCF7L2 (transcription factor 7 like 2)
Diseases named in the same sentence as TCF7L2 in open-access papers (continued):
Sharing a sentence is not in itself a finding about the gene and the disease.
tumor (continued). "Indeed, earlier RNA interference studies supported the proposed tumor suppressor function of TCF7L2, and demonstrated that TCF7L2 may not be strictly required for human CRC cell line survival." (PMID 36609428, 2023). "However, no support for antiproliferative or tumor suppressive activities of TCF7L2 was found." (PMID 36609428, 2023). "Remarkably, these pairwise comparisons also reveal that any link to extracellular matrix (ECM) generally excludes TCF7 and TCF7L2, but generally includes both TCF7L1 and LEF1; TCF7L1 more in normal tissue, and LEF1 more in tumor." (PMID 32403323, 2020).
metabolic disease (22 papers, 2012 to 2025). A congenital disorder (due to inherited enzyme abnormality) or acquired (due to failure of a metabolically important organ) disorder resulting from an abnormal metabolic process. "TCF7L2, a downstream transcriptional effector of the Wnt/β-catenin signaling pathway, has been extensively associated with metabolic disease in human genetic studies." (PMID 37909330, 2023). "In the presentpaper, we have determined the frequencies of the 103894Tand 53341T alleles in gene TCF7L2 associated with DM2 andother metabolic disorders in the populations of Buryats, Yakuts,Dolgans, and Teleuts, as well as a sample of Russians fromEastern Siberia." (PMID 35434484, 2022). "For example, a study demonstrated that remodeling of the ECM in adipose and muscle tissue plays a pivotal role in metabolic disease development, identifying genes such as TCF7L2, ADIPOQ, CD36, PPARG, IL6, SIRT1, and COL5A1 as key regulators of inflammation." (PMID 41303617, 2025). "For instance, the transcription factor (TF) TCF7L2 is a WNT modulator associated with human psychiatric and metabolic disorders." (PMID 37697401, 2023). "The impact of the TCF7L2 gene on metabolic diseases is fundamental because this gene has multiple targets in the pathways for insulin synthesis." (PMID 27230431, 2016). "Gene set enrichment analysis demonstrated that these genes were involved in multiple metabolic processes, including lipid metabolism, carbohydrate, steroid, and ketone, suggesting an essential role of TCF7L2 in metabolic diseases." (PMID 24719615, 2014). "Wnt effectors such as TCF7L2 may be potential targets for therapeutic treatment of Wnt-related metabolic disease." (PMID 35958557, 2022). "As shown by microarray analyses, mRNA levels of the Wnt/β‐catenin signalling target genes related to metabolic diseases, including TCF7L2, WISP‐1, IGF‐1 and PPARδ, were lower in the visceral adipose tissues from patients with T2DM than in tissues from non‐diabetic subjects." (PMID 35384342, 2022). "Given that TCF7L2 has been associated with metabolic disorders and glucose metabolism is affected in PAG by loss of TCF7L2 in Vglut2-positive neurons, metabolic status may influence PAG-USV neuron activities and contribute to mammal vocal production and performance." (PMID 36782064, 2023). "In this study, we found that CXXC5 was specifically induced with suppressing Wnt/β-catenin pathway target genes such as GLP1, TCF7L2, WISP1, and fos-related antigen 1 (FOSL1) in the liver tissues of NASH patients with metabolic disorders." (PMID 36114279, 2022).
cardiovascular disease (10 papers, 2009 to 2025). "The TCF7L2 gene is a significant genetic factor contributing to the risk of metabolic and cardiovascular diseases (CVD)." (PMID 40050721, 2025). "It is reported that TCF7L2 has a strong impact on the breakdown and absorption of glucose and lipids; therefore, it is hypothesized that TT carriers might have a greater chance for developing cardiovascular diseases." (PMID 34724590, 2021).
infection (6 papers, 2012 to 2025). The state of being infected such as from the introduction of a foreign agent such as serum, vaccine, antigenic substance or organism. "Other upstream regulators such as CLU, KLF5, SP1 and TCF7L2 that were inhibited by ΔhtrA mutant infection have also been previously shown to be involved in apoptosis regulation." (PMID 37193047, 2022). "MA10 infection induced seven additional down-regulated (Hsp90aa1, Tcf7l2, Gnas, Sparcl1, Ywhag, Cpe, Sparc) and four upregulated DEGs (Ppp1r1b, Penk, Arpp21, Pcp4), whereas Aβ pathology resulted in five down-regulated (Cplx1, Syp, Meg3, Snhg11, Penk) and one upregulated DEG (Psen1)." (PMID 41497643, 2025). "During infection with the ΔhtrA mutant, CBX5 was activated and CLU, KLF5, SP1, TCF7L2 and UBE2I were inhibited." (PMID 37193047, 2022). "We also found that hepatic glycogen content in 12-week-old male LTCFND mice showed a trend of increase, whereas in mouse primary hepatocytes (MPHs), adenovirus Ad-TCF7L2DN infection but not Ad-TCF7L2 infection increased expression of glycogen synthase 2 (Gys2)." (PMID 31589598, 2019). "Neither insulin tolerance nor plasma insulin levels was changed with expression of TCF7L2, suggesting that global insulin signaling might not be affected by Ad-TCF7L2 M infection." (PMID 23028378, 2012). "Indeed, we did not observe changes in hepatic insulin signaling with Ad-TCF7L2 infection in lean mice, suggesting that TCF7L2 might not directly regulate insulin signaling in the physiological context (data not shown)." (PMID 23028378, 2012).
colon (2 papers, 2017 to 2024). "Moreover, the co‐expression and co‐dependency relationships between SOX9 and TCF7L2 were more pronounced in GBC compared to other gastrointestinal tumors, suggesting a unique interplay between these two TFs in GBC." (PMID 39492805, 2024).
colorectal (2 papers, 2012 to 2020). "Conflicting observations concerning the role of TCF7L2 in colorectal carcinogenesis prompted us to systematically investigate TCF7L2 dependence/independence of CRC cells and the phenotypic consequences of TCF7L2 inactivation." (PMID 32203164, 2020).
neurological disorders (1 paper, 2026). "Our study opens new avenues for exploring TCF7L2 as a potential target in neurological disorders characterized by astrocyte dysfunction and excitability imbalance." (PMID 41351316, 2026).
TCF7L2 also shares sentences with these, for which no sentence is quoted: bipolar disorder (8 papers); leukemia (4); retinopathy (4); liver steatosis (3); non-alcoholic fatty liver disease (3); peripheral artery disease (3); renal carcinoma (3); age-related macular degeneration (2); cholangiocarcinoma (2); colitis (2); kidney disease (2); MODY (2); myopia (2); neurodevelopmental disorder (2); rheumatoid arthritis (2); Small Intestinal Crohn's Disease (2); thyroid cancer (2); acute lymphoblastic leukemia (1); acute T-cell leukemia (1); adenocarcinoma (1); allergic rhinitis (1); amyotrophic lateral sclerosis (1); attention deficit-hyperactivity disorder (1); Autoimmunity (1); autosomal dominant polycystic kidney disease (1); biliary tract cancer (1); brain tumors (1); breast tumors (1); cervical adenocarcinoma (1); cystic fibrosis (1).
A further 49 diseases each share a sentence with TCF7L2 in 1 paper.